CD38 (CD38 molecule)
Diseases named in the same sentence as CD38 in open-access papers (continued):
Sharing a sentence is not in itself a finding about the gene and the disease.
leukemia (continued). "We deepened the analysis of the apoptotic death triggered by BK124.1 into the subpopulations of CML CD34+ cells distinguished by double labeling with anti-CD34 and anti-CD38 antibodies, particularly focusing on the CML CD34+/38− cells corresponding to leukemia stem cells." (PMID 35892900, 2022). "Notably, we proved that CAR.CD123-NK cells significantly eradicated CD123+ cells in all CD38+CD34−, CD38+CD34+, and CD38−CD34+ cell subsets compared to the control conditions (leukaemia alone and NT-NK cells)." (PMID 36335396, 2022). "They finally construct endogenous CD38 knockdown CAR NK cells with promising success in minimizing NK cell fratricide and specifically killing CD38+ acute myeloid leukemia (AML) cell lines and primary leukemia cells." (PMID 36428748, 2022). "However, more recent evidence suggests that only the leukemia-initiating cells are located in the CD34+/CD38− compartment, while the (more proliferative) bulk of the blast cells is located in the CD34+/CD38+ compartment." (PMID 36142442, 2022). "The study could have been more informative if we could profile KIAA0125 expression of healthy CD34 + CD38- HSCs and more mature progenitors (CD34 + CD38- and CD34-CD117+, respectively) and compare those with leukemia blasts." (PMID 33225420, 2021). "As human CD38 was shown to bind to CD31, which is highly expressed on endothelial cells, we assumed a putative role in interference with adhesion and circulation of leukemia cells." (PMID 34764342, 2021). "An early report from a study using CD38-directed CAR T cells in six patients with CD38+ AML relapse following allogeneic HCT showed remissions in four, suggesting clinically meaningful anti-leukemia efficacy." (PMID 33287224, 2020). "Confocal analysis confirmed that HC-NPs can specifically target leukemia KU812 cells in a co-culture and the specific targeting established the importance of the antibody anti-CD38 functionalization of our HC-NPs, in order to improve the efficacy of therapy and to reduce side effects." (PMID 31510037, 2019). "The cellular uptake was time-dependent, and surface functionalization of HC-NPs with anti CD38 antibody revealed an improved cellular uptake for leukemia compared with other NP formulations that do not present the antibody on their surface." (PMID 31510037, 2019). "There are several kinds of leukemia cells, including CD34+CD38− cells and CD34−CD38+ cells." (PMID 30310855, 2018). "The recent inclusion of CD26 as a putative leukemia stem cell marker in CML suggests that going forward, the CD34+/CD38–/CD26+ compartment may be most appropriate for identifying a resistance signature governing deep responses." (PMID 29707154, 2018). "Analogous results were obtained in another leukemia stem-like cell line, CD34+CD38− Kasumi cells." (PMID 28814980, 2017). "These CD34+/CD38− leukemia stem-like cells displayed positivity of the myeloid markers CD13 (99.1%), CD33 (98.6%), and CD123 (93.7%), suggesting that certain myeloid features remain in these sorted CD34+/CD38− KG1α cells." (PMID 28518151, 2017). "Downregulation of Nrf2 and phosphorylation of JNK induced by DS/Cu were markedly blocked by NAC in CD34+CD38− KG1α cells, suggesting that ROS might act upstream of the Nrf2 and JNK pathways in leukemia stem-like cells treated with DS/Cu." (PMID 28518151, 2017). "We sorted the CD34+CD38- cells from the AML cell line KG1a and the CML cell line KU812, as LSCs of myelogenous leukemia are considered to be enriched in this fraction, which was also previously reported in leukemia cell lines including KG1a." (PMID 26784514, 2016). "In our study, CD82 inactivated p38 MAPK and downregulated expression of p16 in leukemia cells, suggesting that CD82 might inhibit senescence in CD34+/CD38− AML cells via inactivation of p38 MAPK signaling and suppression of p16 expression." (PMID 25955299, 2015).
leukemia (continued). "The existence of cancer stem cells was demonstrated in human leukemia, where limiting dilution xenotransplantation of CD34+/CD38− leukemic cells recapitulated the entire original tumor, whereas CD34+/CD38+ and CD34− leukemic cells were not tumorigenic at any cellular concentration." (PMID 25080108, 2014). "Subsequent studies demonstrated that the tumorigenic potential was not restricted to these markers as human CD34+/CD38+ leukemia cells also produced tumors in mice." (PMID 25080108, 2014). "When analyzing the HSC and MPP (CD34+CD38+) compartments, in many cases (6 out of 10) a strong shift from the MEP/CMP compartments towards the GMP was observed, possibly highlighting the myeloid character of the leukemias that were studied." (PMID 19956772, 2009). "RXFP1 expression is markedly elevated in leukemia cells, with 2.71-fold increases in acute myeloid leukemia (AML) and 3.31-fold increases in chronic myeloid leukemia (CML) compared with control populations (CD34+/CD38- stem cells and CD34+/CD38+ progenitor cells)." (PMID 41196672, 2025). "However, MYLS22 did not change the proportion of CD34+CD38- leukemic cell population known to be enriched in leukemia-initiating cells." (PMID 36739349, 2023). "To further investigate the strength of our adoptive immunotherapy, we sought to evaluate whether CAR.CD123-NK cells were able to recognize and eliminate CD34+CD38− AML cells, which are known to represent the leukaemia-initiating cell compartment characterized by high resistance to chemotherapy." (PMID 36335396, 2022). "The identification of a very minor fraction of leukemia marrow cells that have a primitive Lin−, CD34+, CD19−, CD33−, CD38− phenotype and that contained the patient-specific leukemia karyotype suggests that B-cell precursor ALL may arise in a more primitive cell." (PMID 35216407, 2022). "The origin of cancer directly from the normal stem cell was mainly supported by reports that identified the CD34+/CD38- tumor subpopulation as the fraction that can initiate leukemia upon transfer to nonobese diabetic-severe combined immunodeficiency (NOD/SCID) recipient mice." (PMID 34736527, 2021). "Moreover, leukemias could also only be engrafted in mice using primitive CD34+CD38- cells, whereas AML-CFU were most prevalent in the CD34+CD38+ cell population." (PMID 33807298, 2021). "Upon isolation and injection into immunodeficient mice, LSC positive or negative for CD45RA and/or CD38 were able to induce leukemia, indicating that LSC can also be found in populations that phenotypically resemble more mature cells, such as common myeloid or granulomonocytic progenitors (CMP/GMP)." (PMID 33322769, 2020). "CD38 is both a positive and negative prognostic indicator in leukaemia." (PMID 29234114, 2017). "As leukemia-initiating cells (LICs) – most frequently found within the CD34+/CD38− cell compartment – are supposed to be the source of relapse, we next analyzed the expression level of CD157 on CD45DIM, CD34+/CD38− cells of AML patients in comparison to leukemic bulk cells (CD45DIM)." (PMID 28415689, 2017). "However, there have been cases that lacked CD34 or CD38 protein but still had leukemia initiating capacity in B-ALL suggesting the restrictive of these two markers." (PMID 28018598, 2016). "As shown in present studies, the use of pure population of induced lin−CD34+CD90+CD117+-CD45+CD38+/− BCR-ABL+ cells enabled identification of genes affected by imatinib treatment and eventually led to discovery of novel survival factor for primitive leukemia cells OLFM4." (PMID 26561938, 2015). "Initially, as the specific surface markers CD34 and CD38 had been extensively validated in the identification of normal hematopoietic stem cells, these molecules were used as markers in the original studies of leukemia stem cells." (PMID 22359637, 2012).
leukemia (continued). "Specifically, leukemic cells expressing HSC markers (e.g., CD34+CD38−), as opposed to the bulk of leukemia cells, generated blood cancers in mice after transplantation (with self-renewal inferred by the ability to serially transplant the leukemias from mouse to mouse)." (PMID 37832945, 2024). "Furthermore, CD34+CD38+ cells failed to produce leukemia in immunodeficient mice." (PMID 39335624, 2024). "Similarly, we studied the effect of ricolinostat on other tumor cell lines but did not observe an increase in CD38 expression after ricolinostat in lymphoma or leukemia cell lines, indicating that upregulation of CD38 by ricolinostat is a specific effect in MM cells." (PMID 32350373, 2021). "They showed that LSC expressed a higher amount of CD82 than CD34+/CD38+ AML cells; these findings suggested that overexpression of CD82 may render LSC able to adhere to the bone marrow (BM) niche where it appears to regulate maintenance of leukemia stem cells within the BM niche." (PMID 28646224, 2017). "CD133 but not CD19 is expressed on normal primitive fetal hematopoietic stem cell/multipotent progenitors (Lin–CD34+CD38–), while fetal B-progenitors (CD34+CD19+) express CD19 but not CD133, confirming that CD133/CD19 coexpression is leukemia-specific." (PMID 40898981, 2026). "They found the presence of such cells in the primitive CD34+ CD38- but not in the more mature CD34+ CD38+ fraction, suggesting that the leukemia clone is also organized as a hierarchy." (PMID 39272967, 2024). "It was shown that this leukemic stem cell (LSC) population is CD34+CD38- and has a strong ability to reinitiate the same leukemia in mice, whereas CD34+CD38+ cells do not have such an ability." (PMID 38790277, 2024). "A recent study tracking the leukemia cells of AML patients before and after chemotherapy found that CD34+CD38- LSCs and AML blasts were equally eliminated, and LSCs no longer remained quiescent after chemotherapy." (PMID 35865470, 2022). "CD34+ acute myeloid leukemia stem cells are defined as CD38-negative and CD34-positive; although these subpopulations are rare, they are mainly responsible for maintaining leukemia development." (PMID 32586050, 2020). "When these CD25-positive and -negative populations were transplanted into the secondary recipient mice, both CD25-positive and -negative populations established leukemia in which the expression of CD25 and CD38 in Lin–CD34+ cells varied." (PMID 30550585, 2018). "Ouabain, one of the CGs, specifically targeted CD34+CD38− leukemic stem-like cells, but not the more mature CD34+CD38+ leukemic cells, making this type of compounds a potential treatment for leukemia." (PMID 27110755, 2016). "We showed that this leukemia initiating cells subpopulation was not so rare in patients, and we found that FISH+CD34+CD38- cells ranged from 0.01% to 52.8% in the bulk of blasts." (PMID 24517186, 2013). "Although leukemia stem cells have been reported to increase in frequency during treatment in AML, CD34 and CD38 were not among the markers observed to increase, raising a further possibility that our choice of markers precluded the observation of treatment-based selection." (PMID 41295979, 2026). "Indeed, clonal subcultures derived from single B-ALL cells give rise to subpopulations with disparate CD34 and CD38 expression within hours and ultimately reproduce a heterogeneous leukemia regardless of the initial CD34 and CD38 immunophenotype." (PMID 41295979, 2026). "In the 1990s, a detailed investigation of AML subpopulations provided the first proof of a rare LSC population, with a CD34+/CD38- phenotype, within AML capable of establishing leukemia in nonobese diabetic/severe combined immunodeficiency (NOD/SCID) mice: leukemic stem cells (LSCs)." (PMID 35800375, 2022).
leukemia (continued). "Just a small fraction (0.01%) of human AML cells was able to initiate leukemia in nonobese diabetic-severe combined immunodeficient mice, their cell surface phenotype corresponded to that of a normal HSC (CD34++, CD38-), and, like HSCs, the cells that initiated leukemia were able to self-renew." (PMID 36362357, 2022). "Studies from Dick and colleagues were the first to support the hierarchical model of tumorigenesis by showing that sorted CD34+/CD38-, but not CD34+/CD38+ and CD34−, human acute myeloid leukemia (AML) cells injected in mice could give rise to leukemia." (PMID 33451077, 2021). "ARV-825 resulted in reduced BETP-dependent transcription of chemokine receptors, indicated by downregulation of surface CXCR4 and CD44 in leukemia stem cell populations, thereby reducing CD34+CD38– putative leukemia progenitor cell populations without affecting healthy BM–derived progenitor cells." (PMID 33466790, 2021). "Interestingly, surface expression of Tim-3 was significantly elevated in CD34+CD38− AML leukemia stem cells (LSCs) and CD34+CD38+ leukemic progenitors, but not in CD34+CD38− normal HSCs or most portion of CD34+CD38+ normal progenitors." (PMID 31186046, 2019). "Also in CD34 positive AML in the absence of CD34+CD38- cells, but with neoplastic CD34+CD38+ and CD34- populations present, the latter two populations may take over the leukemia initiating ability." (PMID 25244440, 2014).
COVID-19 (181 papers, 2020 to 2025). A disease caused by infection with severe acute respiratory syndrome coronavirus 2. "While patients treated with anti‐CD20 antibodies, BTK‐inhibitors or anti‐CD38 therapy, often fail to respond and are considered to be at high risk for a severe Covid‐19 disease." (PMID 35602247, 2022). "The results demonstrated that the percentage of CD38+HLA-DR+ T cells (OR: 1.13, 95% CI: 1.01-1.26, p = 0.039) was an independent risk factor for death in COVID-19 Patients." (PMID 40370439, 2025). "In summary, the elevated expression of CD38 observed in severe COVID-19 patients is likely linked to its roles in inflammation and immune regulation." (PMID 39852780, 2024). "Both CD4 + and CD8 + T cells demonstrated increased expression of cell surface markers of activation (CD38 + and HLA-DR+) associated with G-MDSCs in children with acute COVID-19 requiring admission to the ICU (r = + 0.63, r = + 0.67, respectively)." (PMID 35733812, 2022). "As reported, the transitional differentiation of naive into effector/memory T cells co-expressing CD38+HLA-DR+ among CD8+T cells is a hallmark of COVID-19 that persisted in LVS compared to controls and SVS (P = 0.002 and P = 0.012)." (PMID 34230615, 2021). "Of note, HLA-DR+ CD38+ co-expression on CD8+ T-cells was significantly associated with COVID-19 severity in a cohort of 125 COVID-19 patients." (PMID 34222849, 2021). "There was also a trend towards increased risk for poor NAb response following COVID-19 vaccination with anti-CD38-based regimens (OR: 2.4, 95% CI: 2.9–6.2, p = 0.07)." (PMID 34341335, 2021). "We found that T cell activation, characterized by expression of CD38, was a hallmark of acute COVID-19." (PMID 34975885, 2021). "The expression of CD38 and Ki67 was inversely associated with the time COVID-19 patients spent in clinical care (P = 0.0006, r = –0.39; and P = 0.017, r = –0.27, respectively, data not shown)." (PMID 33945513, 2021). "It has been reported that the disease severity of COVID-19 is associated with dysregulation of CD38+, HLA-DR+, or PD-1+ CD8+ T cells." (PMID 33362779, 2020). "In present study, we identified a unique T cell subset, the CD38+HLA-DR+ T cells, that could serve as an independent risk factor of 28-day mortality in COVID-19 patients." (PMID 40370439, 2025). "During the immunopathogenesis of COVID-19, this may cause the accumulation of immune cells in the lungs and may culminate in a likely CD38-mediated thrombosis." (PMID 36675642, 2023). "Importantly, similar to our findings, severe COVID-19 was also associated with strongly increased protein expression of the activation markers CD38, CD69, and HLA-DR in early disease." (PMID 37712059, 2023). "CD38+ plasma B cells were initially sorted and analyzed to focus on the characterization of the activation-associated transcriptional signatures in plasma cells during COVID-19 progression." (PMID 35899045, 2022). "Hyperinflammation in COVID-19 may lead to CD38 activation and NAD+ degradation, predisposing to severe outcomes, including tissue fibrosis and tissue damage, particularly in the elderly." (PMID 36077708, 2022). "When applied to a flow cytometry dataset profiling CD8+ T cells in COVID-19 patients and healthy controls, treekoR highlighted a highly activated HLA-DR+ CD38+ CD8+ T cell subset whose %parent provided a more robust association with COVID-19 response than its %total." (PMID 34844647, 2021). "Considering that some data suggest that CD8+ T cells may have a hyperactivation signature in patients with severe COVID-19, this might imply that strong CD38+HLA-DR+ or Ki67+ T cell activation could underline virus-specific CD8+ T cell responses in those patients." (PMID 36986364, 2023).